AKT1 (AKT serine/threonine kinase 1)
Diseases named in the same sentence as AKT1 in open-access papers (continued):
Sharing a sentence is not in itself a finding about the gene and the disease.
colitis (43 papers, 2016 to 2025). Inflammation of the colon. "The subsequent comprehensive in silico analysis revealed the ability of TM to bind to the active sites of key colitis-associated regulators, including Akt1, Src, STAT3 and dopamine receptor D2." (PMID 32455822, 2020). "This implies that colitis might be associated with the interaction of Akt1 and Akt2, which are important kinases mediating DSS-induced apoptosis." (PMID 36831001, 2023). "Berberine has been found to play a regulatory role in macrophage M1 polarization in DSS-induced colitis through the AKT1-suppressor of cytokine signaling-1 (SOCS1)-NF-κB signaling pathway." (PMID 34149863, 2021). "Involvement of Akt1 in colitis as revealed by our study is one such example." (PMID 28659381, 2017). "Overall, our data support the role of SUMOylation in DSS-induced colitis in mice and highlights the hypothesis that lowering of Akt1 SUMOylation correlates with severely decreased levels of Ubc9." (PMID 28659381, 2017). "To clarify these problems, we detected the levels of PI3K, p-PI3K, AKT1, and p-AKT1 in colitis mice, and results showed that DSS stimulation strongly induced PI3K/AKT activation as indicated by the elevated phosphorylation of PI3K and AKT1." (PMID 38689349, 2024). "Though BBR’s efficacy on colitis has been verified in plentiful ways, for instance, BBR represses macrophage M1 polarization via the AKT1/SOCS1/NF-κB pathway for prevention of dextran sodium sulfate (DSS) -stimulated colitis." (PMID 35259053, 2022). "Akt1, which is related to these multiple signaling pathways, may be a hub contributing to improved DSS-induced colitis after ALL treatment." (PMID 36831001, 2023).
renal carcinoma (43 papers, 2015 to 2025). A carcinoma arising from the epithelium of the renal parenchyma or the renal pelvis. "The expression level of AKT1 was decreased in renal cancer and GIST." (PMID 28258440, 2017). "Additionally, it has been documented that PTEN/PI3K/Akt1 signaling regulates YY1 expression, at least in renal cancer cells." (PMID 39063014, 2024).
Hypertension (42 papers, 2012 to 2025). The presence of chronic increased pressure in the systemic arterial system. "AKT1 is associated with hypertension, and AKT1 mutations greatly increase the risk of hypertension." (PMID 37664830, 2023). "MAPK1 and AKT1 are able to facilitate vascular endothelial cell proliferation and angiogenesis, which is closely related to hypertension." (PMID 38496269, 2024). "Of these, TNF, MMP9, and AKT1 have been reported to be involved in hypertension and considered important genes that function in the effect of gastrodin on hypertension." (PMID 37495624, 2023). "The same results were obtained by incubating VSMCs isolated from normotensive animals with angiotensin II (regulator of hypertrophic signals during hypertension), which is a key activator of Akt1 in VSMCs." (PMID 23150829, 2012). "Combined with protein interaction network analysis, the potential primary targets of berberine in treating hypertension may include AKT1, BCL2, EGFR, STAT3, and TNF." (PMID 41567631, 2025). "Based on the results of the network analysis and molecular docking, we found that AKT1, VEGFA, eNOS, ICAM-1, PTGS2, and ALB may also be associated with the potential effects of GZD on hypertension." (PMID 33906674, 2021). "Also, Angiotensin II involved in the development of cell contraction and eventually of hypertension, regulates polyploidization in this cell type as well as the hepatocyte through the Akt1 pathway." (PMID 27727291, 2016). "The occurrence of hypertensive disorder complicating pregnancy can be caused by the decrease of the expression of MMP9 in the network, and AKT1, ESR1, FOS, VEGFA and other proteins play an important role in the pathogenesis of hypertensive disorder complicating pregnancy, such as preeclampsia." (PMID 34062719, 2021).
endometriosis (41 papers, 2018 to 2026). The growth of functional endometrial tissue in anatomic sites outside the uterine body. "Previous research demonstrated increased transcription of the AKT1 and 4EBP1 genes in the eutopic endometrium of endometriosis patients, suggesting a possible role for these genes in endometrial growth outside the uterus." (PMID 35408777, 2022). "Therapeutic agents targeting ESR1 are now under phase 3 clinical trials in endometriosis, and thus, we further performed attack analysis in the context of AKT1 + ESR1, with maximal network disconnection (~16%) achieved by 3-node removal." (PMID 35401535, 2022). "AKT1 was one of common hub genes among 3 endometriosis subtypes in our study, indicating that the outcome of text mining was partially consistent with DEG analysis, but it also provided some unique findings." (PMID 34917684, 2021). "The top 6 genes associated with endometriosis found in our study are CDKNB2, MAPK1, WNT4, ILA, AKT1, and KRAS." (PMID 29750165, 2018). "In endometriosis, some studies, including our own, suggest upregulation of AKT1, which may cause induction of the AKT signaling pathway." (PMID 35204508, 2022). "Calpain7 promotes nuclear exclusion of FOXO1 by hydrolyzing AKT serine/threonine kinase 1 (AKT1) and inhibits decidualization of human endometrial stromal cells in endometriosis." (PMID 38795132, 2024). "AKT-1 immunolocalization in ectopic and eutopic endometrium of patients with endometriosis and endometrial tissues of control patients without endometriosis." (PMID 41567980, 2025). "The identification of AKT1, or more generally, genes in the PI3K/AKT/mTOR pathway (including MTOR, PIK3CA, and PIK3R1 in addition to ATK1), is in line with current interests targeting this pathway in endometriosis." (PMID 35401535, 2022). "In a study comparing the expression levels of relevant angiogenesis-related genes in the eutopic endometrium of women with and without endometriosis, high AKT1 levels were observed as compared with controls." (PMID 29750165, 2018).
Hepatic steatosis (41 papers, 2011 to 2026). Steatosis is a term used to denote lipid accumulation within hepatocytes. "AKT1 deficiency led to the inhibition of AKT/mTOR/S6K signaling pathway in hepatocytes, which was crucial for the development of hepatic steatosis and provided a new scheme for the development of NAFLD therapy." (PMID 36866057, 2023). "The Akt1-mediated increase in muscle mass led to reductions in fat mass and hepatic steatosis in older animals, and corrected age-associated impairments in glucose metabolism." (PMID 24033924, 2014). "The fact that hypermuscularity induced by elevated Akt1 activity reduced hepatic steatosis in mice fed a high-fat diet suggests that this is an indirect consequence of hypermuscularity rather than a direct effect of reduced activin receptor activity in liver." (PMID 21390326, 2011). "Akt1 transgene activation in aging mice led to the selective hypertrophy of type IIb fibers, restored lean muscle mass, improved metabolic parameters, and diminished the extent of hepatic steatosis." (PMID 24033924, 2014).
rheumatoid arthritis (41 papers, 2008 to 2026). A chronic, systemic autoimmune disorder characterized by inflammation in the synovial membranes and articular surfaces. "The inhibition of the PI3K/Akt-1 pathway has been shown to induce synovial macrophage apoptosis in rheumatoid arthritis." (PMID 37937143, 2023). "According to the results of molecular docking, in the context of rheumatoid arthritis, phytocannabinoids may bind to important target proteins such as PIK3CA, AKT1, MAPK9, PRKCD, BRAF, IGF1R, and NOS3." (PMID 36983855, 2023).
Anxiety (40 papers, 2013 to 2026). Intense feelings of nervousness, tension, or panic often arise in response to interpersonal stresses. "The disease severity, anxiety, and suicidal tendencies in depressive patients were associated with AKT1 polymorphism." (PMID 38505421, 2024). "The results which combined network pharmacological analysis and molecular docking showed that the effects of treating PTSD and anxiety of beta-sitosterol, Tenulin, Fumarine, and Stigmasterol were associated with AKT1 and IL-6." (PMID 37986356, 2023). "Specifically, under the effects of THC, we found greater functional activation in fear processing-related brain regions and more severe associated anxiety, as a function of increasing AKT1 methylation." (PMID 34573260, 2021). "Conditional Akt1 deficiency in excitatory neurons impairs contextual fear LTM but does affect anxiety-related behaviors or fear extinction processes." (PMID 33325370, 2020). "Together these OFA and EPM data demonstrate that Akt1 and Akt2 deficiency affect the expression of anxiety-related behaviors in a sex-specific fashion." (PMID 33325370, 2020). "We find that AKT1 loss more broadly affects neural function, impacting anxiety-related behavior, spatial memory, extinction learning, and renewal in Akt1 KO mice but only the males." (PMID 33325370, 2020). "Following up on these results, we then show that activation of Akt1, a central hub in the insulin pathway, alleviates long‐term memory decline and ameliorates altered anxiety levels in the APP/PS1 transgenic AD mouse model." (PMID 37984409, 2023). "Overall, these tests with 5xFAD transgenic mice suggest that activation of Akt1 in AD mice can recover long‐term memory deficits and attenuate dysregulated anxiety levels." (PMID 37984409, 2023). "AKT1 affects anxiety-like behaviour in a sex-specific fashion, which the male Akt1 KO mice increased anxiety-like behaviour." (PMID 35098831, 2022). "It was found that MAPK, AKT1, and IL-6 in the serum of patients with anxiety were all increased, and there was a significant positive correlation between anxiety severity and sleep quality." (PMID 34660782, 2021). "The present study extends such findings indicating that the rs1130233 polymorphism of the AKT1 gene also moderates the acute effects of THC on the neurophysiological underpinnings of fear processing and associated anxiety-like behaviour." (PMID 34573260, 2021). "Male and female mice with single-isoform deletions of Akt1, Akt2, or Akt3 were assessed for anxiety-related behaviors in the open field arena (OFA) and elevated plus maze (EPM) tests." (PMID 33325370, 2020). "For instance, while Pdyn is the only gene positively correlated with anxiety-like behavior in XX mice, Htr1a, Cdk5, Adcy2, Akt1, Akt2, and Akt3 positively correlate with anxiety-like behavior in XY- mice." (PMID 24199867, 2013). "Consistent with these important roles of Akt1 in insulin signaling, our experiments demonstrate that activation of Akt1 with the small molecule SC79 increases viability of HEK293 cell expressing ND‐causing genes, and enhances long‐term memory and ameliorates dysregulated anxiety levels in AD mice." (PMID 37984409, 2023). "Additionally, researchers found that quercetin could inhibit neuronal apoptosis to preventing anxiety-like behaviors in vivo via regulating the Akt1 and ASK1/JNK3/caspase-3 expression." (PMID 32256358, 2020). "This may explain the synergistic effects of Akt1 and Akt3 removal on memory and why Akt1 removal alone was sufficient to affect anxiety-like behavior and fear extinction: GABAergic mechanisms linked to interneuronal function were shown previously to mediate these behaviors." (PMID 33325370, 2020). "It should be noted that a series of control experiments regarding normal profiles of basic behavioral phenotypes was reported previously in Akt1+/− or Akt1−/– mice and in Nrg1+/− mice, such as locomotor activity, anxiety-like behavior, olfactory function, and sensorimotor gating function." (PMID 25688191, 2014).
Anxiety (continued). "In our study, 17 core common targets of ACG and anxiety were predicted, of which ESR1, SRC, AKT1, MAPK8, EGFR, and MMP9 belong to the prolactin and estrogen signaling pathways." (PMID 35624976, 2022). "Like AKT1, AKT2 affects anxiety-like behavior in a sex-specific fashion and impacts contextual memory." (PMID 33325370, 2020). "In addition, molecular docking results indicated that beta-sitosterol and Fumarine were the crucial bioactive components, and AKT1 and IL6 were potential target genes for treating the same pathogenesis of anxiety and PTSD by KXS." (PMID 37986356, 2023). "Based on PPI network analysis, AKT1 and IL-6 might be the crucial target genes for the overlapping pathology of PTSD and anxiety." (PMID 37986356, 2023). "Altered expression of the AKT1 gene may therefore influence sensitivity to the effects of THC on brain functioning and related behavior, especially anxiety-related manifestations." (PMID 34573260, 2021). "In addition, quercetin can inhibit neuronal apoptosis by regulating the expression of AKT1 and ASK1/JNK3/Caspase-3, thus preventing anxiety behavior." (PMID 34479552, 2021). "When we assessed anxiety-like behavior in Akt1 cKO Akt3 KO mice, we found no performance differences in the OFA or EPM compared to WT controls for either sex." (PMID 33325370, 2020). "Basic behavioral profiling of Akt1 KO mice showed that there are no overall motor, anxiety and widespread cognitive behavioral deficits, although displaying abnormal working memory involving the hippocampus." (PMID 28442992, 2017). "Although AKT1 and EGFR were predicted to be involved in anti-anxiety processes in our study, the two targets have not been shown to be directly involved in the anti-anxiety process." (PMID 35624976, 2022).
ischemia (39 papers, 2009 to 2025). A hypoperfusion of the BLOOD through an organ or tissue caused by a PATHOLOGIC CONSTRICTION or obstruction of its BLOOD VESSELS, or an absence of BLOOD CIRCULATION. "When ischemia occurs, the activity of Akt1 can be abolished." (PMID 29651017, 2018). "There were 10 active constituents against ICVD, including quercetin, luteolin, kaempferol, and naringenin, and 10 important targets for anticerebral ischemia, namely, PIK3CA, APP, PIK3R1, MAPK1, MAPK3, AKT1, PRKCD, Fyn, RAC1, and NF-κB1." (PMID 35432563, 2022). "The specific AKT-mediated phosphorylation of MDM2 at Ser166 induced by IPC was confirmed by using a small interfering RNA (siRNA) specifically designed against AKT1 protein (siAkt), highly expressed in cortical neurons, and whose activity is essential for neuronal survival after ischemia." (PMID 34298892, 2021).
prostate tumors (38 papers, 2007 to 2025). "AKT1/MYCN-mediated progression was also associated with the development of invasive metastatic castration-resistant prostate tumors." (PMID 37370720, 2023). "Previous work in PTEN-deficient prostate tumors demonstrated their dependence on AKT2 for both maintenance and survival, but AKT1 in the same tumors was dispensable." (PMID 37894325, 2023). "It has been demonstrated that Akt1 activity is higher in primary prostate tumors compared to normal prostate tissues." (PMID 35406397, 2022). "Levels of Akt1 increased in metastatic prostate tumors compared to matched primary tumors in 7 out of 8 patients." (PMID 34591413, 2021). "Briefly, levels of Akt1 and Akt2 were increased in metastatic tumors compared to primary prostate tumors, while levels of Akt3 decreased." (PMID 34591413, 2021). "A low dose of Akt1 or Akt2 inhibitor enabled standard chemotherapies to significantly eradicate metastatic prostate tumors in a mouse model, acting as chemosensitizers." (PMID 34591413, 2021). "A mutational profiling of AKT1 and of the mutational hotspots in PIK3CA and PIK3R1 was carried out in samples from primary and recurrent prostate tumours." (PMID 20407443, 2010). "Ablation of AKT1 decreases prostate tumor growth in vivo but enhances formation of lung metastases." (PMID 31752925, 2019). "Akt1 ablation prevents prostate tumour onset in Pten+/− mice." (PMID 28082369, 2017). "Unlike AR, STRADA, TTK, and AKT1 showed little evidence of gene amplification or loss in human prostate tumors." (PMID 22509301, 2012). "Of the 218 prostate tumors, 34.4% had reduced expression of STRADA, 18.3% exhibited overexpression of TTK, 11.7% either overexpressed or had reduced expression of AKT1, and 15.6% of tumors overexpressed or had amplified AR." (PMID 22509301, 2012). "The large number of prostate tumors with alterations in STRADA, TTK, and AKT1 expression led us to look at their correlation with biochemical recurrence." (PMID 22509301, 2012). "In the resultant MPAKT/Hi-MYC model, AKT1 and MYC are expressed together in the prostate, recapitulating the co-incidence of the genetic lesions in human prostate tumor samples." (PMID 21394210, 2011).
psoriasis (38 papers, 2008 to 2026). An autoimmune condition characterized by red, well-delineated plaques with silvery scales that are usually on the extensor surfaces and scalp. "Case with psoriasis has homozygous DCLRE1C, heterozygous ZAP70, RFX5, AKT1, and NOD2 gene variants, and all of them were VUS variants." (PMID 39992598, 2025). "Many studies have shown that the excessive proliferation of psoriasis keratinocytes was closely related to the increase of AKT1 levels in skin lesions." (PMID 35265149, 2022).
acute lymphoblastic leukemia (37 papers, 2008 to 2025). Leukemia with an acute onset, characterized by the presence of lymphoblasts in the bone marrow and the peripheral blood. "This study examined pediatric T-cell acute lymphoblastic leukemia (T-ALL) samples for PTEN and AKT1 gene variations and evaluated the clinical findings." (PMID 31744268, 2020).
squamous cell carcinoma (37 papers, 2008 to 2026). A carcinoma arising from squamous epithelial cells. "Myristoylated AKT1 (myr-AKT1) overexpression and N-MYC mutation result in the development of prostate adenocarcinoma, squamous carcinoma, and NEPC." (PMID 37282627, 2023). "In our study population, AKT1 and PIK3CA mutations were only found in squamous cell carcinomas, with frequencies of 2.6% and 10.5%, respectively." (PMID 31668020, 2019). "However, it was also reported that the down-regulation of AKT1 was involved in squamous cell carcinomas (SCC) and human papillomavirus (HPV) infection." (PMID 40564394, 2025).
diabetic cardiomyopathy (35 papers, 2014 to 2025). Diabetic cardiomyopathy is a disorder of the heart muscle in people with diabetes. "If impaired mitochondrial AKT1 is an underlying cause of cardiomyopathy, we hypothesized that, by maintaining its regulatory activity while in a diabetic state, we could attenuate or even prevent the development of diabetic cardiomyopathy." (PMID 37891673, 2023). "Activation of mitochondrial AKT1 in CAMCAKT had a protective role against diabetic cardiomyopathy as well as improved metabolism beyond the heart." (PMID 37891673, 2023).